ENSG00000267426 (novel protein)
Gene: Protein-coding gene on chromosome 17 (75,898,645 to 75,930,129, reverse strand). Ensembl gene ENSG00000267426.
Genetic constraint (gnomAD): Missense variants: 64 observed, 60.62 expected, observed/expected ratio (o/e) 1.06, 90% interval 0.86 to 1.3. Synonymous variants: 24 observed, 22.66 expected, observed/expected ratio (o/e) 1.06, 90% interval 0.77 to 1.49.